ELANE (elastase, neutrophil expressed)
Diseases named in the same sentence as ELANE in open-access papers (continued):
Sharing a sentence is not in itself a finding about the gene and the disease.
abscess (2 papers, 2023 to 2025). An inflammatory process characterized by the accumulation of pus within a newly formed tissue cavity which is the result of a bacterial, fungal, or parasitic infection or the presence of a foreign body. "In a recent analysis of the proteomic components of different abscess regions, neutrophil surface markers and multiple neutrophil-specific antimicrobial factors—including CTSG and ELANE—were detected in the abscess at the host–pathogen interface." (PMID 37118737, 2023).
cholesteatoma (2 papers, 2014 to 2015). A pathologic process characterized by the proliferation of keratinizing squamous epithelium resulting in the accumulation of keratin and cells in the middle ear and/or mastoid. "This is also likely the scenario for our observation of increased ELANE in cholesteatoma-involved bone." (PMID 26608071, 2015). "Both cholesteatoma and the neck of cholesteatoma showed higher levels of ELANE compared to EACS, and higher, but more inconsistent levels, compared with the tympanic membrane." (PMID 25093596, 2014). "Due to the finding of increased levels of neutrophil elastase (ELANE) in cholesteatoma, we constructed a network of related proteins meeting the criteria for differential protein level in one or both of the comparisons of cholesteatoma vs. EACS or neck of cholesteatoma vs. EACS." (PMID 25093596, 2014). "Neutrophil elastase (ELANE) and extracellular matrix protein 1 (ECM1) proteins were up-regulated in cholesteatoma." (PMID 25093596, 2014).
diabetic retinopathy (2 papers, 2025). "ELANE, a serine protease secreted by neutrophils, is thought to alter vascular permeability and be involved in vascular leakage, particularly in diabetic retinopathy." (PMID 40641746, 2025).
endometrial cancer (2 papers, 2021 to 2025). Primary or metastatic malignant neoplasm involving the endometrium (mucous membrane that lines the endometrial cavity). "The heatmap in endometrial cancer showed that ELANE and GSDMD were upregulated and GPX4 and TIRAP were downregulated." (PMID 34722500, 2021).
Kawasaki disease (2 papers, 2019 to 2022). A rare inflammatory disease characterized by an acute febrile, systemic, self-limiting, medium-vessel vasculitis primarily affecting children. "By acting on ELANE, aspirin can treat Kawasaki disease by eliminating the inflammatory response and maintaining the integrity of the innate immune barrier." (PMID 35990842, 2022). "The tight binding results showed that ELANE was also an important target of aspirin in the treatment of Kawasaki disease." (PMID 35990842, 2022). "In the study, 13 core targets (such as CTSG, ELANE, and FGF1) highly related to Kawasaki disease and aspirin were identified by bioinformatics method." (PMID 35990842, 2022). "The experimental results suggested that aspirin can treat Kawasaki disease by regulating inflammatory response by acting on CTSG, FGF1, and ELANE." (PMID 35990842, 2022). "In conclusion, bioinformatics analysis and computer simulation research indicated that CTSG, ELANE, and FGF1 were key targets of aspirin in Kawasaki disease." (PMID 35990842, 2022). "In the treatment of Kawasaki disease, aspirin may regulate inflammatory response and vascular remodeling through CTSG, ELANE, and FGF1." (PMID 35990842, 2022). "We find that aspirin treats Kawasaki disease through CTSG, ELANE, and FGF1." (PMID 35990842, 2022).
liver cancer (2 papers, 2021 to 2025). An epithelial or non-epithelial malignant neoplasm that arises from the liver. "These insights align closely with our finding that ELANE may mediate the relationship between cheese consumption and liver cancer risk." (PMID 40895144, 2025). "Protein‐level analyses identified four trogocytosis‐ and efferocytosis‐related proteins, TGFB3, EPOR, ELANE, and C3, that may mediate these dietary effects on liver cancer susceptibility." (PMID 40895144, 2025). "This study uncovers a potential molecular mechanism by which FODMAP‐related dietary patterns may modulate liver cancer risk through the TGFB3/EPOR/ELANE/C3 signaling axis." (PMID 40895144, 2025). "MR findings suggest that higher cheese intake is associated with reduced liver cancer risk, with partial mediation through modulation of TGFB3, EPOR, ELANE, and C3 expression." (PMID 40895144, 2025). "Mediation MR indicated that cheese intake influenced liver cancer risk indirectly by modulating TGFB3, EPOR, ELANE, and C3 expression, accounting for 8.8%, 25%, 1.8%, and 12.7% of the total effect, respectively." (PMID 40895144, 2025). "Using a two‐step MR framework, we evaluated whether TGFB3, EPOR, ELANE, and C3 mediate the causal association between FODMAP dietary intake and liver cancer risk." (PMID 40895144, 2025). "Furthermore, these findings emphasize the pivotal roles of TGFB3, EPOR, and ELANE in liver cancer, especially regarding dietary factors such as cheese intake." (PMID 40895144, 2025). "The MR results revealed significant associations between three FODMAP dietary components, cheese, cereal, and dried fruit intake, and six liver cancer‐related proteins (ANXA2, SFTPD, TGFB3, EPOR, ELANE, and C3)." (PMID 40895144, 2025).
mouth ulcers (2 papers, 2023 to 2025). "In conclusion, the ELANE mutation is a common cause of CN or SCN, with clinically manifestations ranging from recurrent fever, infections to oral ulcer, lymphadenitis." (PMID 37118811, 2023).
myeloid malignancies (2 papers, 2024). "We present 5 patients that received MSD-BMT using a reduced toxicity busulfan and fludarabine conditioning regimen for ELANE-mutant SCN without myeloid malignancy." (PMID 38469307, 2024).
alcohol use disorder (1 paper, 2025). "In conclusion, our study provides the first clinical validation demonstrating a significant association between elevated plasma ELANE levels and alcohol use disorder, underscoring its potential role in AUD pathophysiology." (PMID 41369182, 2025). "We are the first to demonstrate that plasma ELANE is involved in the pathogenesis of alcohol use disorder." (PMID 41369182, 2025). "Plasma neutrophil elastase(ELANE) was markedly elevated in patients with alcohol use disorder, indicating a dysregulated protease‐antiprotease inflammatory balance characterised by decreased SERPINA3." (PMID 41369182, 2025). "Given the central role of inflammation in alcohol‐related neurotoxicity, ELANE represents a biologically plausible and previously underexplored biomarker candidate for alcohol use disorder." (PMID 41369182, 2025). "The group with alcohol use disorder had considerably higher ELANE concentrations than the healthy controls (p < 0.001)." (PMID 41369182, 2025). "ELISA was used to verify that the concentration of ELANE in patients with alcohol use disorder was significantly higher than that in healthy controls (p < 0.001)." (PMID 41369182, 2025). "Patients were categorized as high ELANE (≥ 2.7651 pg/mL, n = 46) or low ELANE (< 2.7651 pg/mL, n = 44) based on the median ELANE expression level in the alcohol use disorder group." (PMID 41369182, 2025). "Our previous studies have identified ‘ELANE’ as the Hub gene in alcohol use disorder." (PMID 41369182, 2025). "Our previous research has identified ‘ELANE’ as a key gene for alcohol use disorder." (PMID 41369182, 2025). "This study was conducted to investigate the potential role of the ELANE gene in alcohol use disorder, which may be a potential biomarker or therapeutic target for alcohol use disorder." (PMID 41369182, 2025).
Cachexia (1 paper, 2020). Severe weight loss, wasting of muscle, loss of appetite, and general debility related to a chronic disease. "Four were common for local/cachexia (C1R, PRKCG, ELANE, SOST: all oppositely regulated) and four for metastatic/cachexia (SERPINA6, PDGFRA, PRSS2, PRSS1: all consistently changed), suggesting that stage and cachexia status might be molecularly separable." (PMID 33334063, 2020).
familial Mediterranean fever (1 paper, 2017). Familial Mediterranean fever (FMF) is an autoinflammatory disorder characterized by recurrent short episodes of fever and serositis resulting in pain in the abdomen, chest, joints and muscles. "Pretransplant investigations revealed ELANE mutation positive severe CyN along with familial Mediterranean fever (MEFV) mutation." (PMID 28197346, 2017).
Intraventricular hemorrhage (1 paper, 2024). Bleeding into the ventricles of the brain. "Three out of seven ELANE/CXCL16-treated E13.5 embryos showed intraventricular hemorrhage." (PMID 39349662, 2024).
Kostmann disease (1 paper, 2015). "Mutations in ELANE, the gene for neutrophil elastase, account for the majority of autosomal dominant SCN while mutations in the gene encoding the HAX-1 protein account for the autosomal recessive forms, also known as Kostmann disease." (PMID 26119962, 2015).
meningioma (1 paper, 2020). A generally slow growing tumor attached to the dura mater. "Proteins involved in neutrophil degranulation, such as ARSA, GCA, FUCA1, PRTN3, ELANE, MNDA, and LCN2, were identified uniquely or with differential abundance in male meningiomas." (PMID 32587372, 2020).
parvovirus infection (1 paper, 2022). "Likewise, a novel ELANE mutation associated with inflammatory arthritis, defective NETosis, and recurrent parvovirus infection was recently described." (PMID 36284314, 2022).
periodic fever syndrome (1 paper, 2017). Fevers of unknown etiology recurring over months or years. "We suggest CyN patients who present with severe symptoms have evaluation with ELANE mutation testing, Periodic Fever Syndromes Panel, and routine marrow assessment with FISH, conventional cytogenetics, and morphological evaluation for MDS/AML." (PMID 28197346, 2017).
Sjögren’s syndrome (1 paper, 2025). "Garreto and colleagues also revealed a significant increase in the levels of Matrix Metalloproteinase-9 (MMP9), Neutrophil Elastase (ELANE), Cathepsin G (CTSG), and Myeloblastin (PRTN3) in the saliva of patients with Sjögren’s syndrome compared to healthy controls." (PMID 41301757, 2025).
T cell deficiency (1 paper, 2022). "In contrast to T cell deficiency, the recurrent tumors were significantly enriched for markers of tumor-associated neutrophils (TANs; eg., CD177, ELANE), tumor-associated macrophages (TAMs; eg., MRC1, CD68), and immune suppressive myeloid cells (MDSCs; eg., ARG1, CXCR4)." (PMID 35919862, 2022).
tumor (290 papers, 2003 to 2026). "Therefore, high levels of ELANE expression were considered to be risk factors in many types of tumor." (PMID 37596368, 2023). "However, further research is needed to determine the specific mechanism that leads to the association between high expression of ELANE in tumor tissue and poor prognosis." (PMID 37596368, 2023). "However, the high expression of ELANE in tumor tissue was associated with poor prognosis." (PMID 37596368, 2023). "Mechanistically, in co-culture with tumor cells, downregulation of TPM2 on tumor cells increases neutrophil elastase (ELANE) levels in neutrophils regulated by p38/ MAPK signaling activation, and ELANE promotes tumor cell progression through the Hippo pathway." (PMID 40199876, 2025). "In accordance with dd-ABPP results, the data showed a significant elevation of ELANE activity in tumor samples of both survival types, but with differences related to slightly higher activity in long-term– compared with short-term subtypes." (PMID 40425563, 2025). "Consistently, our immune profiling analyses using both CIBERSORT and xCell demonstrated that high-risk AML patients exhibit a higher proportion of M2 macrophages, further reinforcing the clinical relevance of ELANE in modulating the tumor microenvironment." (PMID 40748972, 2025). "In vivo studies have demonstrated that ELANE not only attenuates primary tumor growth but also inhibits distant metastasis through an abscopal effect mediated by CD8+ T cells, underscoring its significant immunomodulatory properties." (PMID 40748972, 2025). "ELANE exerts its anti-tumor effects by promoting the apoptosis of cancer cells, while simultaneously increasing the presence of tumor dendritic cells (DCs), CD8+ T cells, and CD8+ T effector cells (CD8+ Teffs)." (PMID 40282474, 2025). "ELANE is one of the key components that take part in the control of the innate immune system, and it participates in the regulation of tumor progression through various mechanisms." (PMID 38205232, 2024). "Neutrophils in contact with tumor targets have been found to have a number of tumoricidal mechanisms that include releasing ROS or neutrophil elastase (ELANE)." (PMID 39439807, 2024). "Granular cytoplasmic staining of ELANE was found in neutrophils within cancer crypts, ulcers, inflammatory infiltrates and microabscesses in most of the tumours examined (89% of primary VSCC, 48/54)." (PMID 37118737, 2023). "Through a comprehensive bioinformatics analysis of GC transcriptome data, we found that the high expression level of ELANE was closely related to the tumor progression of GC." (PMID 37596368, 2023). "After evaluating the correlation between tumor immune infiltration, we found that M1 macrophages in ELANE low expression group were obviously increased; meanwhile, M1 macrophages can effectively kill the tumor cells." (PMID 37596368, 2023). "We applied the CIBERSORT computing method to analyze the relationship between ELANE and tumor immune-infiltrating cells (TIICs)." (PMID 37596368, 2023). "When the expression level of ELANE in tumor and normal tissues of the same GC patient was compared, the expression of ELANE in normal tissues was also obviously higher than that in tumor (p < 0.001)." (PMID 37596368, 2023). "We found that memory CD4 T cells and resting mast cells were also obviously increased in the ELANE high-expression group; however, the tumor infiltration of these cells was related to poor prognosis in tumor patients." (PMID 37596368, 2023). "Amplifying tumor cell killing activity of ELANE/PPE while retaining precise targeting capacity is needed to achieve maximal therapeutic effect." (PMID 37031242, 2023). "ELANE can not only directly regulate tumor cell behavior, and is involved in the tumor-host interactions and the tumor metastasis." (PMID 37596368, 2023). "Most genes were highly enriched in tumor tissues, while only 4 genes including ELANE, IL6, IL1B and NLRP3 were upregulated in normal tissues." (PMID 36267972, 2022).
tumor (continued). "In summary, we developed and optimized a formulation of tumor cell-specific exosomes (HELA-Exos) to specifically transfer the TLR3 agonist Hiltonol and the ICD inducer ELANE into tumor cells." (PMID 35148751, 2022). "Except for ELANE, which was expressed at low levels in tumour tissues, the remaining genes were highly expressed in tumours." (PMID 35923703, 2022). "In this study, the combination of diverse mouse models clearly demonstrated that ELANE can attenuate tumor growth in vivo." (PMID 34599140, 2021). "NETs releasing neutrophils eventually release PGE2, IL-8, matrix metalloproteinase-9 (MMP9), ELANE and other tumor promoters plausibly accounting for a more invasive growth of neighboring tumor cells." (PMID 32098278, 2020). "Additionally, ELANE-mediated tumor cell death releases tumor antigens, enhancing dendritic cell activation and promoting CD8+ T cell priming, which target distant metastases through a systemic anti-tumor immune response." (PMID 41009604, 2025). "Additionally, active neutrophil elastase (ELANE) has been shown to suppress primary tumor growth and generate a CD8+ T-cell-mediated abscopal effect, targeting distant metastases." (PMID 40282474, 2025). "Also, ELANE, a neutrophil elastase, a major anticancer protein enabling neutrophils to specifically kill tumor cells, was downregulated." (PMID 38398111, 2024). "Finally, significant ELANE activity was also detected in Clinical Proteomics Tumor Analysis Consortium datasets of solid tumors (many of which have known myeloid infiltration)." (PMID 38219859, 2024). "The significant downregulation of ELANE observed in the tumor samples assessed was probably related to the inhibited tumor immunity in the BC patients, which is in accordance with a previous study, and with our analysis of the DEGs between the high-risk and low-risk groups." (PMID 37511974, 2023). "ELANE might be participate in the change of TIME from immunodominant to metabolically dominant and its expression was closely related to tumor mutation burden and multiple TIICs." (PMID 37596368, 2023). "In addition, the mechanism of ELANE's influence on GC progression and tumor immune invasion needs to be further clarified." (PMID 37596368, 2023). "ELANE (elastase, neutrophil expressed), which regulates the functions of NK cells, monocytes, and granulocytes, could kill tumor cells and suppress tumorigenesis." (PMID 37511974, 2023). "ELANE might affect the GC patients’ prognosis by affecting the tumor immune cell infiltration in the TIME." (PMID 37596368, 2023). "ELANE also can degrade insulin receptor substrate 1 and activate the phosphatidylinositol 3 kinase-protein kinase B signaling pathway, thereby promoting the proliferation of tumor cells." (PMID 37596368, 2023). "In this study, the expression level of ELANE was higher in normal tissues than tumor tissues." (PMID 37596368, 2023). "Considering that the nucleo-cytoplasmic translocation of histone H1 plays a crucial role in precision tumor discrimination and killing effect of ELANE/PPE, we hypothesized that accelerating histone H1 translocation would enable maximal therapeutic effect." (PMID 37031242, 2023). "Therefore, ELANE also acts at the limit between tumor cells and the vasculature, leading to a decrease in the clearance of tumor cells inside the blood circulation." (PMID 37596368, 2023). "Indeed, this study revealed that three serpins secreted by cells in the tumor microenvironment (TME), including A1AT, SERPINB1, and SLPI, can antagonize ELANE’s anti-tumor capability in a dose-dependent manner." (PMID 34599140, 2021). "Additionally, ELANE has been found to suppress primary tumor growth effectively." (PMID 40282474, 2025). "Further, ELANE facilitates the proteolytic liberation of the CD95 death domain, which interacts with histone H1 isoforms to specifically destroy tumor cells." (PMID 40282474, 2025).